PIGR (polymeric immunoglobulin receptor)
Diseases named in the same sentence as PIGR in open-access papers (continued):
Sharing a sentence is not in itself a finding about the gene and the disease.
colon carcinoma (11 papers, 1996 to 2025). "The same study individuates as a unique feature in IBD colon cancer the hypermethylation and consequent loss of function of the polymeric immunoglobulin receptor (PIGR), which is responsible for the transport of IgA and IgM through the epithelium." (PMID 39359726, 2024). "This possibility agreed with Southern blot analysis performed on a separate sample of 32 other colonic carcinomas in which the diallelic loss of D1S58 (which exhibits a close linkage centromerically to PIGR) was calculated to be 6.4%." (PMID 8664120, 1996). "The interferon-stimulated response element (ISRE) in the exon 1 of PIGR gene in HT-29 human colon carcinoma cells binds IRF-1 following the stimulation of IFNγ to enhance the transcription of pIgR." (PMID 35493520, 2022). "Decreased PIGR expression has been found in colon tumours, while RGMA has been reported to have an inhibitory effect on cancer progression." (PMID 29642861, 2018). "The human polimeric immunoglobulin receptor (PIGR) was found to be underexpressed in colon tumors and also in colon tumor cell lines." (PMID 23049694, 2012). "However, human colon carcinoma cells maintained pIgR expression on the basolateral side on the external part of the pseudo-lumen structures." (PMID 29156712, 2017). "High levels of the cleaved extracellular domain of pIgR, designated as the secretory component, have also been detected in the sera of patients with lung and pancreatic cancer, as well as patients exhibiting colon cancer with liver metastases." (PMID 24699841, 2014). "PIGR has been previously studied in HCC, colon cancer, pancreatic cancer, osteosarcoma, and glioma, where its high expression has been associated with unfavorable prognoses." (PMID 39202022, 2024). "Colon cancer cells RKO and HCT8 overexpressing PIGR protein were shown sensitive to cisplatin but not to oxaliplatin." (PMID 40724830, 2025).
asthma (10 papers, 2021 to 2025). "In COPD, asthma or CF there are multiple alterations and defects affecting the pIgR/IgA axis, contributing to the diseases." (PMID 37051237, 2023). "In asthma (type-2 inflammation), the expression of pIgR is downregulated due to IL-4 and IL-13 release by Th2-cells." (PMID 37051237, 2023). "Mucin-7, Mucin-5B, Immunoglobulin J chain, polymeric immunoglobulin receptor, filaggrin and hornerin were differentially altered in asthma and asthma with chronic rhinosinusitis condition compared to control." (PMID 34414402, 2021). "IL-4 and IL-13 were found to downregulate polymeric immunoglobulin receptor (pIgR) at the site of IgA binding on airway epithelial cells, suggesting that IgA levels may be reduced in asthma." (PMID 37445635, 2023). "Supporting a beneficial role of sIgA in chronic inflammatory airway diseases, such as asthma, are reports that the pIgR is downregulated in eosinophilic upper airway diseases and that bronchial secretion of IgA is impaired in the airways of asthma patients due to the downregulation of pIgR." (PMID 37759430, 2023). "Conversely, our group reported a reduced pIgR expression in the bronchial epithelium from patients with asthma, with in vitro experiments indicating that IL-4R activation (and thus a type 2 immune environment) may account for this epithelial defect in asthma." (PMID 35386640, 2022). "For instance, IL-4 may stimulate pIgR expression in Calu-3 cell line cultures, while it inhibits pIgR expression in primary airway epithelial cells, contributing to pIgR downregulation found in the airway epithelium of asthma patients." (PMID 35456002, 2022). "The pIgR/IgA system is altered in several chronic respiratory diseases, such as chronic obstructive pulmonary disease (COPD), asthma, and cystic fibrosis." (PMID 35456002, 2022). "In contrast with asthma or COPD, epithelial polarity-related pIgR expression was unexpectedly upregulated in lung tissue (explants) from patients with end-stage CF." (PMID 34248677, 2021). "We will then develop how the dysregulation of pIgR/IgA mucosal immunity could impact the pathogenesis and clinical course of chronic airway diseases such as COPD, asthma, and CF." (PMID 35456002, 2022). "In addition, inflammatory cytokines contribute to pIgR downregulation both in asthma and COPD, while IL-17 conversely upregulates pIgR in Pseudomonas aeruginosa (Pa) infected CF cells." (PMID 35456002, 2022). "Interestingly, those data are contrasting with previous findings in asthma where pIgR down-regulation, although being similarly present in situ, does not persist in ALI, suggesting distinct mechanisms driving epithelium pathology in asthma and COPD." (PMID 38158219, 2024).
Cirrhosis (10 papers, 2014 to 2024). A chronic disorder of the liver in which liver tissue becomes scarred and is partially replaced by regenerative nodules and fibrotic tissue resulting in loss of liver function. "PIGR mRNA was significantly upregulated in HDV-related cirrhosis in GSE98383 compared to cirrhosis samples from GSE14323 (p < 0.001)." (PMID 33937393, 2021). "On the contrary, PIGR was downregulated in cirrhosis compared to that in healthy individuals in GSE14323 (p < 0.05)." (PMID 33937393, 2021). "PIGR mRNA was upregulated in advanced liver fibrosis, cirrhosis compared to normal liver (all p < 0.05)." (PMID 33937393, 2021). "Strikingly, PIGR increased in abundance in all our three cohorts in line with the severity of liver damage and the up‐regulation is most dramatic in cirrhosis." (PMID 30824564, 2019). "Furthermore, a global correlation map of clinical and proteomic data strongly associated DPP4, ANPEP, TGFBI, PIGR, and APOE with NAFLD and cirrhosis." (PMID 30824564, 2019). "Additionally, PIGR was overexpressed in cirrhosis compared to nonalcoholic fatty liver disease." (PMID 33937393, 2021). "Thus, PIGR might promote the processes of liver fibrosis, cirrhosis, and hepatocarcinogenesis in the chronic liver diseases." (PMID 33937393, 2021). "Interestingly, the level of PIGR was up‐regulated in all three cohorts and 128% higher in the cirrhosis group compared to NAFLD, consistent with the notion that increased PIGR levels may be a novel marker of disease progression (Fig EV1C)." (PMID 30824564, 2019). "Polymeric immunoglobulin receptor (PIGR) is significantly increase in non-alcoholic fatty liver disease and cirrhosis." (PMID 38429802, 2024). "used plasma proteome profiling technology and identified elevated PIGR in both NAFLD and cirrhosis and a correlation of DPP4, ANPEP, TGFBI, PIGR, and APOE with the diseases." (PMID 39188279, 2023). "PIGR was significantly higher in HCC patients with nodular formation and incomplete cirrhosis (p < 0.001) and established cirrhosis (p < 0.05)." (PMID 33390805, 2021). "Increased serum amyloid A1 abundance was previously reported in mice fed a high-fat diet for 6 months, and polymeric immunoglobulin receptor was identified as a candidate plasma biomarker for human NAFLD and cirrhosis." (PMID 34762911, 2021). "The inter‐individual variation in plasma PIGR levels in controls was relatively small, much lower than that in the NAFLD and cirrhosis cohorts." (PMID 30824564, 2019). "In accordance with the increased levels of PIGR in patients with NAFLD, we also observed up‐regulated immunoglobulin chains in cirrhosis, among which most are derived from IgA, IgM, and IgG." (PMID 30824564, 2019). "Polymeric immunoglobulin receptor (PIGR) was significantly elevated in both cohorts by 170% in NAFLD and 298% in cirrhosis and was further validated in mouse models." (PMID 30824564, 2019). "Among the interesting similarities between patients with cirrhosis and patients with NAFLD was PIGR, a little studied protein produced in the GI tract and endothelial cells but also in the liver." (PMID 30824564, 2019). "Conversely, PIGR mRNA was downregulated in cirrhosis samples than that in normal liver in Mas Liver dataset (p < 0.0001)." (PMID 33937393, 2021). "Plasma proteome profiling of 48 patients with and without cirrhosis or NAFLD revealed six statistically significantly changing proteins (ALDOB, APOM, LGALS3BP, PIGR, VTN, and AFM), two of which are already linked to liver disease." (PMID 30824564, 2019). "pIgR expression is frequently increased in response to viral or bacterial infections, and HBV antigen-induced hepatocyte damage, followed by regeneration of hepatocytes, fibrosis and ultimately cirrhosis, are important events in hepatocellular carcinogenesis." (PMID 25397670, 2014).
colorectal cancer (9 papers, 2014 to 2025). A primary or metastatic malignant neoplasm that affects the colon or rectum. "PIGR expression is significantly downregulated and associated with favorable prognosis in nasopharyngeal carcinoma (NPC) and colorectal cancer." (PMID 40386563, 2025). "High expression of PROM1, LEMD1, CLDN2, PIGR and LCN2 were associated with CRC cell migration, promoting colorectal cancer growth and metastasis." (PMID 36816926, 2023). "In previous studies, LAMB3 was also reported to promote tumor progression and chemoresistance through the AKT-FOXO3/4 axis and be transcriptionally regulated by the BRD2/acetylated ELK4 complex and polymeric immunoglobulin receptor in colorectal cancer." (PMID 36612197, 2022). "In this context, the correlation between protein and mRNA levels of PIGR seems to be good and decreased levels of both in malignant as compared with benign tissue has been observed in previous studies on e.g. lung and colorectal cancer." (PMID 25397670, 2014). "PIGR suppresses colorectal cancer through the AKT-FOXO3/4 axis by downregulating LAMB3 expression, which may provide a clue for molecular treatment for CRC." (PMID 35992840, 2022). "This study aimed to investigate whether PIGR is essential for colorectal cancer (CRC)." (PMID 36157233, 2022).
ovarian carcinoma (9 papers, 2013 to 2024). A malignant neoplasm originating from the surface ovarian epithelium. "In this pooled, prospective population-based cohort of epithelial ovarian cancer, significant associations were found between PIGR expression and mucinous histology, low-grade tumours and Ki-67 expression, indicating a less aggressive phenotype for tumours displaying high PIGR expression." (PMID 24568264, 2014). "Significant relationships between PIGR expression and low-grade tumors were also discovered in a prospective population-based cohort of epithelial ovarian cancer, demonstrating a less aggressive character for tumors with high PIGR expression." (PMID 38136890, 2023). "The expression and prognostic significance of PIGR, an immunoglobulin receptor, is similar, in epithelial ovarian cancer." (PMID 31182966, 2019). "Kaplan-Meier analysis and Cox regression analysis were applied to examine the impact of PIGR expression on overall survival (OS) and ovarian cancer-specific survival (OCSS)." (PMID 24568264, 2014). "Furthermore, IgA-based immunotherapies could be more effective than conventional IgG-targeted interventions against ovarian cancer or other pIgR+ mucosal tumours." (PMID 33536615, 2021). "High expression of the polymeric immunoglobulin receptor (PIGR) has previously been associated with a favourable prognosis in a few cancer forms, but its expression and relationship with clinical outcome in epithelial ovarian cancer (EOC) has not yet been reported." (PMID 24568264, 2014). "Collectively these data demonstrate that IgA produced in the ovarian cancer microenvironment contributes to thwarting malignant progression through both antigen recognition, and via non-specific transcytosis through pIgR+ tumour cells." (PMID 33536615, 2021). "Interestingly, proteins such as CCNE1, FASN, HDGF, MCM7, PIGR, PTK2, or TRA2B have been described as having a prognostic relation with some other type of gynecological cancer (breast, cervical or ovarian cancer)." (PMID 34680205, 2021). "To determine whether IgA–pIgR interactions elicit transcytosis through tumour cells, we first incubated pIgR+ OVCAR3 ovarian cancer cells with fluorescently labelled non-antigen-specific IgA or IgG." (PMID 33536615, 2021).
viral infection (8 papers, 2013 to 2024). "Our previous research found that pIgR is a receptor of WSSV for viral infection via the pIgR-CaM-Catherin endocytosis pathway." (PMID 36067252, 2022). "It has been shown that IgA can be internalized by the polymeric immunoglobulin receptor (pIgR) on the surface of epithelial cells, bind to the newly generated viral proteins in the cells, and inhibit virus assembly, thus resisting the virus infection." (PMID 32811334, 2020). "In the mucosa, secretory IgA is transported to mucosal surface by polymeric Ig receptor (pIgR) and the secreted IgA plays an important role in the protection of viral infection in the respiratory tract." (PMID 24324462, 2013). "Some pathogens have even evolved to hijack pIgR to promote viral infection." (PMID 39066171, 2024). "By contrast, in a recent study pIgR knock-out mice showed a reduced acute norovirus infection rate, suggesting that pIgR and natural polymeric immunoglobulins may promote viral infections." (PMID 30984170, 2019). "It has been demonstrated that IgA can be internalized within epithelial cells by the polymeric immunoglobulin receptor (pIgR), and inside the cell it can be able to bind to newly synthesized viral proteins, preventing viral assembly and neutralizing viral infection." (PMID 25140692, 2014). "Since dimerization is a unique feature that SARS-CoV-2 ORF8 has acquired but that is absent in the ORF8 of SARS-CoV and other coronaviruses, it is speculated that SARS-CoV-2 ORF8 may be more effective in dampening pIgR-mediated mucosal immunity and thus better assist viral infection and spread." (PMID 39066171, 2024). "Besides, the decrease of Ig alpha-1 chain C and of polymeric immunoglobulin receptor (pIgR) that we observed could have promoted the viral infection/immunological alteration." (PMID 24088505, 2013).
endometrial cancer (7 papers, 2013 to 2023). Primary or metastatic malignant neoplasm involving the endometrium (mucous membrane that lines the endometrial cavity). "One study revealed associations between early-stage endometrial cancer and high PIGR expression, proposing a possible explanation for this less aggressive type." (PMID 38136890, 2023). "Other estrogen-responsive genes upregulated in CTCF-altered cancers, namely SPDEF, TFF3 and PIGR, are also components of these gene signatures, indicating that loss of CTCF could be an important factor determining endometrial cancer progression and pathology." (PMID 30513694, 2018). "Furthermore, the expression of estrogen-responsive genes KIAA1324, MLPH, MSX2, SPDEF, TFF3, and PIGR were all significantly up-regulated in CTCF-altered endometrial cancers (p = 0.0004, 0.0007, 0.0032, 0.0009, 0.0122, and 0.0028 respectively)." (PMID 30513694, 2018). "Furthermore, loss of PIGR expression has been linked to tumour progression in non-small cell lung cancer while overexpression of PIGR has been associated with the less aggressive type 1 endometrial cancer as well as correlating with a better prognosis in bladder cancer and epithelial ovarian cancer." (PMID 24694107, 2014).
lung carcinoma (7 papers, 2015 to 2025). "The loss of pIgR expression is associated with cell proliferation and poor prognosis in lung cancer." (PMID 34617407, 2021). "Decreased expression of pIgR might also be involved in other pathological processes of HIV/AIDS, such as lung cancer." (PMID 28271669, 2017).
pancreatic cancer (7 papers, 2014 to 2024). "Downregulation of PIGR in pancreatic cancer cells markedly changed cellular morphology and reduced cellular proliferation, adhesion, migration and invasion." (PMID 37789066, 2023). "pIgR has recently been demonstrated to be upregulated in pancreatic cancer cells upon exposure to stromal cells in vitro, but to the best of our knowledge, the expression and prognostic significance of pIgR has not yet been described in pancreatic cancer." (PMID 25397670, 2014). "Reducing PIGR expression markedly decreases cell proliferation in pancreatic cancer cells." (PMID 37789066, 2023). "The reciprocal relationship between pIgR and E-cadherin was also confirmed in an analysis of 51 human ductal pancreatic cancer samples (TMA), further indicating a link between pIgR and EMT also in pancreatic cancer, but the associations with pIgR expression and clinical outcome were not described." (PMID 25397670, 2014). "Along this line, given the fact that an extensive desmoplastic stromal reaction is one of the hallmarks of pancreatic cancer, it may be hypothesized that elevated pIgR expression exerts tumour-promoting effects also in pancreatic and periampullary adenocarcinoma." (PMID 25397670, 2014).
chronic obstructive pulmonary disease (6 papers, 2017 to 2025). A chronic and progressive lung disorder characterized by the loss of elasticity of the bronchial tree and the air sacs, destruction of the air sacs wall, thickening of the bronchial wall, and mucous accumulation in the bronchial tree. "Additionally, reduced PIGR expression has been reported in the lung tissue of patients with chronic obstructive pulmonary disease, where it was suggested to be linked to TGF-β –driven reprogramming of airway epithelial cells." (PMID 39762268, 2025). "Mice deficient in pIgR expression are reportedly unable to control infections of the airway by some bacteria, which could drive progressive chronic obstructive pulmonary disease (COPD) phenotype in these mice." (PMID 28271669, 2017). "The level of plasma pIgR is elevated under pathological conditions including biliary cholangitis, chronic obstructive pulmonary disease, malignant tumors and most recently acute respiratory distress syndrome (ARDS)." (PMID 40642082, 2025). "Furthermore, PIGR acts as an important inflammatory mediator and is involved in the pathogenesis of liver fibrosis, pneumococcal meningitis, and chronic obstructive pulmonary disease (COPD)." (PMID 40386563, 2025). "Earlier studies have showed that plasma pIgR was elevated in chronic sterile (or non-infectious) inflammatory diseases, including chronic obstructive pulmonary disease, biliary cholangitis and acute coronary syndrome." (PMID 40642082, 2025).
colitis (6 papers, 2013 to 2025). Inflammation of the colon. "For example, in one patient suffering from pan-colitis, we found four distinct PIGR mutations in four biopsies from the right, transverse, and left side of the colon." (PMID 32697969, 2020). "L. johnsonii-derived EVs restore mucosal immune balance in colitis through a coordinated EV–taurine–Th17/Treg–PIGR/FcRn–IgA/IgG axis." (PMID 41023976, 2025). "Our findings of enrichment of mutations in PIGR, ZC3H12A, and in the IL-17 and TLR pathways suggest there are distinct selection mechanisms in the colitis-affected colon, and somatic mutations potentially play a causal role in the pathogenesis of IBD." (PMID 32697969, 2020). "It has also been reported that knockout of pIgR exacerbates DSS-induced colitis." (PMID 39188786, 2024). "Mice deficient in the polymeric immunoglobulin receptor (Pigr−/−), which facilitates IgA transport into the lumen, are characterized by reduced luminal IgA and altered gut microbiota, promoting higher susceptibility to dextran sodium sulfate (DSS)-induce colitis." (PMID 33562334, 2021). "Finally, by establishing the DSS colitis mouse model and giving FMT treatment, it was found that the increase in the percentage of IgA-binding bacteria in DSS colitis mice may be related to the increase in IgA secretion, independent of pIgR expression." (PMID 35814647, 2022).